CXCL8 (C-X-C motif chemokine ligand 8)
Diseases named in the same sentence as CXCL8 in open-access papers (continued):
Sharing a sentence is not in itself a finding about the gene and the disease.
infection (continued). "As a first step, an investigation was launched into whether M. leprae was able to induce the secretion of the chemokines MCP-1 (CCL2) and IL-8 (CXCL8) in alveolar type II pneumocytic epithelial A549 cells, known to play an important role in mediating immune cell migration to the infection site." (PMID 34456901, 2021). "Our study indicated that short-term-HCV high-viral-load infection induces the expression of genes implicated in cell death and apoptosis via MAPK signaling, and HCV persistence induces the expression of genes that alter cell adhesion and promote migration via the CXCL8-SRC signaling pathway." (PMID 34680563, 2021). "In fact, intestinal mucosal immune responses in the host are activated shortly after an infection, and during this process, a number of pro-inflammatory cytokines and chemokines are expressed and released, including monocyte chemoattractant protein-1, IL-8/CXCL8, and tumour necrosis factor (TNF)-β." (PMID 33663613, 2021). "Additionally, CXCL8 has been demonstrated by others to be upregulated following infection." (PMID 32251473, 2020). "The activation of NF-κB and expression of TNF-α at the infection site in C. albicans-infected fish, combined with the qPCR data showing that the chemokines CXCL8 and CCL2 were upregulated only in C. albicans infection, suggested that phagocytes might be recruited only to C. albicans infections." (PMID 31088918, 2019). "Therefore, it seems the typical presentation of human patients infected with either virus includes high levels of CXCL10, CCL2, IL-6, and CXCL8 in the plasma, peripheral blood leukopenia, and lung neutrophilia, and this is also similar to experimental infection of laboratory animal models." (PMID 28553293, 2017). "Airway epithelial cells activated a panel of antimicrobial genes in a β-glucan-mediated response to A. fumigatus, and secreted TNF-α, IL-8 (CXCL-8) and GM-CSF, indicating an important role for these cells in neutrophil recruitment that is essential for protection from invasive infection." (PMID 25954267, 2015). "As demonstrated here, the expression of IL-8/CXCL8, Gro-α/CXCL1, MCP-2/CCL8 and MIP-3α/CCL20 was compromised in LPS-stimulated IRAK4-deficient monocytes, suggesting a diminished recruitment of neutrophils, monocytes, lymphocytes, basophils and eosinophils to sites of infection." (PMID 20105294, 2010). "In urine, we found increases in IL-1RA, G-CSF, and chemokines CXCL10, CCL4, CCL11, GROα/β/γ, and IL-8/CXCL8, with IL-1RA and CCL4 showing direct correlation with the degree of pyuria at the time of infection." (PMID 41810365, 2026). "The capacity of early and mature retinal organoids to respond to T. gondii tachyzoite infection was determined by RT-qPCR for human cytokine transcripts CCL2, CXCL8, CXCL10, and interleukin-6 (IL6)." (PMID 40137771, 2025). "The heightened infection risk in GD may be attributable to dysfunction of immune cells, including monocytes, macrophages, dendritic cells, T cells, and B cells, as well involvement of cytokines, such as MCP1/CCL2, CXCL8/IL8, CXCL1, IL-1β, IFNγ, and TNFα, are implicated in GD progression." (PMID 40980139, 2025). "Consistent with clinical observations, in vitro infection of RD cells and in vivo infection of suckling mice in our study similarly demonstrated significant upregulation of IL-6, TNF-α, CXCL2, CXCL3, CXCL8 (IL-8), and CXCL10." (PMID 40872743, 2025). "PMNs are the first cells that react in case of infection, attracted by chemotactic stimuli [e.g., formylated peptides, CXCL8/IL-8, lipopolysaccharide (LPS)] released during the inflammatory process." (PMID 40396174, 2025). "Chemokines, including CXCL8, CCL20, and MIF, recruit immune cells, such as neutrophils, macrophages, and T cells, to sites of infection and inflammation and play critical roles in the immune response to pathogens (45, –, 48)." (PMID 41081505, 2025).
infection (continued). "We quantified serum levels of IL-4, IL-6, IL-8/CXCL-8, IL-27, CCL-2, CXCL-9, CXCL-10, and IgG using Luminex and ELISA assays during the acute and subacute phases of infection." (PMID 40711072, 2025). "infection and present in the CM Ba, CM Bs, and CM Bm, might be involved in wound closure inhibition, we preincubated CM from infected cells and CM NI for 1 h with two concentrations of neutralizing antibodies against CXCL8 and CCL2 (0.5 and 1 μg/mL) before repeating the wound healing assay." (PMID 40943115, 2025). "CXCL10 and CXCL8 and CCL-5 are proinflammatory chemokines that play critical roles in the pathogenesis of infection, and function as prognostic indicators of coronaviruses severity." (PMID 40181980, 2025). "Infection with L. monocytogenes led to a significant increase in the mRNA levels of IL6, CXCL8, TNF, and IFNG (p < 0.01 for IL6, p < 0.001 for other cytokines), along with a significant decrease in transcription level of IL10 (p < 0.001)." (PMID 41376047, 2025). "The chemokines (CCL2, CXCL1, CXCL8, and CCL20) facilitate the recruitment of monocytes and neutrophils to the site of infection." (PMID 40570043, 2025). "To assess whether proinflammatory chemokines induced by decidual cell infection contribute to the reduced ability of trophoblasts to form tubular structures, we repeated the tubulogenesis assays by pre-incubating the CM with neutralizing antibodies against CXCL8 and CCL2." (PMID 40943115, 2025). "Interleukin-8 (IL-8), also known as CXCL8, is a proinflammatory chemokine traditionally recognized for its role in recruiting neutrophils to sites of infection, which was identified in 1987–1988." (PMID 41155383, 2025). "Macrophages and monocytes produce high levels of chemokines (CCL2, CXCL8, CXCL10, etc.)that can recruit other innate and adaptive immune cells to the site of infection." (PMID 40472051, 2025). "Infection with viruses, including rhinoviruses, influenza viruses and SARS-CoV-2, increases CXCL8 expression and secretion." (PMID 39962077, 2025). "CXCL8 binds to the receptors CXCR1 and CXCR2, which helps recruit and activate neutrophils to areas where there is inflammation or infection." (PMID 40943634, 2025). "Chemokines, such as CXCL8 (IL-8) and CCL2, direct the movement of critical immune cells, such as neutrophils and monocytes, into tissues to combat infection." (PMID 39702433, 2024). "Nectin-1 was redistributed, at the protein level, in adjacent uninfected cells surrounding infection, inducible by CCL3, IL-8 (or CXCL8), and possibly CXCL10 and IL-6, thus facilitating spread." (PMID 38857290, 2024). "Increased levels of chemokines like CXCL8 and CCL2 promote the recruitment of immune cells to the site of infection, aiding in parasite clearance." (PMID 38694310, 2024). "Expression of IL-6, IL-8 (CXCL8), CXCL1, CXCL2, and CCL-20, which are known to be expressed in the respiratory epithelium upon infection, was assessed." (PMID 38756230, 2024). "The upregulated expression of the C3 and ZC3H12A genes and upregulated expression of antiviral genes, such as CXCL8 and NEURL3, occurred at 9 h post-infection." (PMID 39872814, 2024). "Infection with BRSV leads to an increase in several cytokines and chemokines in circulation, including IL-6, TNF-α, IL-18, chemokine-x-c motif ligand (CXCL8), CCL2, CCL3, and CCL5, mediating the subsequent influx of leukocytes, predominantly neutrophils." (PMID 39599867, 2024). "The observed infiltration of immune cells after infection with swH1N1 agrees with the upregulation of chemotactic factors (AMCF-II, CXCL8/IL8, CXCL2, CXCL10, and CCL20) and their receptors (CCR1 and CXCR2) at the transcriptional level." (PMID 39247193, 2024). "Chemotactic cytokines (chemokines), including CXCL8 and CCL2, attract immune cells, such as neutrophils and monocytes, to the site of infection." (PMID 38694310, 2024).
infection (continued). "The pro-inflammatory cytokine interleukin-8 (IL8) primarily acts as a chemokine (CXCL8), activating and attracting immune cells, particularly neutrophils to sites of infection or injury." (PMID 39513858, 2024). "Following infection by EV30, the choroid plexus epithelial cells secrete a set of chemokines, including CXCL8 (IL-8)." (PMID 38874395, 2024). "IL-8, also known as C-X-C motif chemokine ligand 8 (CXCL8), is initially known as a CXC chemokine recruiting neutrophils into areas of inflammation, infection, or injury and therefore driving the acute inflammatory response." (PMID 37760903, 2023). "For example, a cytokine receptor (CSF3R) and three chemokines (CXCL8, CXCL14, CCL20) responsible for leukocyte trafficking were upregulated during infection only in birds from less-tolerant populations." (PMID 37294834, 2023). "Expression of other genes that were strongly upregulated after infection with most mycobacteria included SERPINB1, CXCL2, CXCL8, CXCL10, and LCN2." (PMID 37822359, 2023). "Infection with KSHV induces high levels of pro-inflammatory cytokines, chemokines and angiogenic factors such as TNF, IL-1α, IL-1β, IL-6, CXCL8, IFN-γ, VEGF, COX-2 and GM-CSF." (PMID 36634147, 2023). "The results showed that mRNA expressions of CXCL8 and TNF in hPBDMs infected with both fungi were significantly induced beginning from 4 h post-infection and the inductions were time-dependent." (PMID 37695039, 2023). "Both decidualized and non-decidualized cells increased their production of CXCL-8 (IL-8) and MCP-1 in response to infection with either wild-type B. abortus or a double mutant for the BtpA and BtpB proteins involved in TLR signaling modulation." (PMID 38133333, 2023). "Vitamin D signaling also activates cytokine production, including interleukin 1β (IL1β) and IL8/CXCL8, during infection." (PMID 36678493, 2023). "Subsequently, other pro-inflammatory cytokine genes were also induced, such as IL-6 and CXCL8, TNFA, IL23, and GM-CSF, with distinct functions in the inflammatory response following infection." (PMID 37237836, 2023). "The results revealed that CXCL8 and CXCL10 cytokine expressions were significantly increased from 8 h post-infection while TNF cytokine level remained similar after infection." (PMID 37695039, 2023). "Similar to 12 h, genes significantly upregulated in the later stages of infection were cytokines or chemokines, such as CXCL1, CXCL2, CXCL3, CXCL8, CXCL10, and CCL20." (PMID 37211158, 2023). "After 48 h of infection, the levels of TNF, CXCL8, IL6, CSF2, CD180, CD14, and CCL2 levels increased and those of IL-10, INFB1, and CXCL10 decreased." (PMID 36296238, 2022). "Many chemokines are produced during the infection process, and specific cell types are recruited through several unique chemokine receptors, such as CXCL1, CXCL2, and CXCL8, which can recruit neutrophils." (PMID 35493728, 2022). "IL-6, CXCL8, and IL-10 mRNA expression induced by ASFV-ΔH240R infection was increased by approximately 5-, 5-, and 10-fold, respectively, compared with ASFV-WT." (PMID 34787458, 2022). "CXCL-8 and TNF-α are directly involved in the recruitment of additional macrophages to the infection site, which results in the breaking of the endothelial barrier." (PMID 35446128, 2022). "We analyzed the secretion or expression of different immunomediators (cytokines CCL2, CXCL8, TNF-α, and interferon-stimulated gene ISG15) at different times following infection of PAMS." (PMID 35019713, 2022). "Local immune responses to RV16 infection include the release of interferons and other pro-inflammatory mediators such as CXCL-10 and CXCL-8 leading to infiltration of inflammatory cells." (PMID 36296939, 2022). "Interleukin-8 (IL-8, also called CXCL8) is a chemokine-induced by infection and produced by macrophages and other cells and is a neutrophil chemotactic factor." (PMID 35889173, 2022).
infection (continued). "The proteomics and Luminex data showed that various macrophage and neutrophil related cytokines and chemokines like MCP-1, IP-10 (CXCL10), MIG, MIP-1β (CCL4), CXCL8 (IL-8), SAA2, and AXL were dramatically upregulated at 7 days after infection." (PMID 35903092, 2022). "In both iBEC-LMC and iBEC monocultures, CXCL8, CXCL1, CXCL2, and CCL20 were upregulated during the time course of infection, with higher upregulation of CXCL8 and CXCL1 in the monoculture model at 24 h p.i.." (PMID 36289516, 2022). "In vitro, infection of Vero-E6 cells with SARS-CoV-2 induced senescence (SenTraGor), DNA damage (γ-H2AX) and increased cytokine (IL-1β, IL-6, CXCL8) and apolipoprotein B mRNA-editing (APOBEC) enzyme expression." (PMID 35086840, 2022). "In the case of tissue injury and/or infection neutrophils follow the gradient of chemoattractants, such as CXCL8 (IL-8) that determines the direction of neutrophil migration into the tissues." (PMID 35163413, 2022). "We have previously suggested that NK cells do not have a role in the direct control of the mycobacteria growth of Mtb, however, the contact between NKs and DCs during infection by M. bovis increases the production of IFN-γ, TNF-α, CCL2, CCL4, and CXCL8." (PMID 35456728, 2022). "ELR-type chemokines activated by cp strain infection included CXCL1, CXCL3, CXCL5, CXCL8, and CXCL15." (PMID 35746747, 2022). "Interleukin 8 (IL-8), or chemokine (C-X-C motif) ligand 8 (CXCL8) is a pro-inflammatory chemokine produced by various cell types to recruit leukocytes to the sites of infection or tissue injury." (PMID 34901094, 2021). "Infection with the als3Δ/Δ and ece1Δ/Δ single mutants induced significantly less secretion of CXCL8/IL-8, CCL20, IL-1α, and IL-1β than the wild-type parent strain." (PMID 33471869, 2021). "Multiple factors contribute to neutrophil recruitment from the circulation to the site of infection, including proinflammatory cytokines (such as IL-1α, IL-1β, TNF-α, and IL-6) and Cxcr2 chemokines (such as Cxcl1, Cxcl2, Cxcl5, and Cxcl8)." (PMID 34011393, 2021). "At these conditions only one gene was detected as significantly up-regulated after infection, NLRP2, and four genes were down-regulated (ALDH3A1, CXCL8, IL1R2, KRT15)." (PMID 34785679, 2021). "Only 4 genes overlapped both time points that also increased expression across MOIs (CXCL1, CXCL2, CXCL8 and IL6), indicating their importance as immune mediators against infection." (PMID 34001998, 2021). "Later studies showed a role for heat shock protein (HSP) 27 in infection by HAdV-D37 in a signalosome that included p38 and NFκB p65; siRNA knockdown of HSP27 reduced CXCL8 expression." (PMID 34960773, 2021). "Upon infection of WD-AECs with RSV-A2 or RSV-ON1-H1, the basolateral cytokine secretion revealed mainly CXCL10/IP-10 and CXCL8/IL-8 release." (PMID 34320038, 2021). "Gene expression analysis revealed a significant induction in pro-inflammatory cytokine transcription in keratinocytes during infection with S. aureus with induction of IL1A (p < 0.05), IL6 (p < 0.01), and CXCL8 (p < 0.05) at early time points." (PMID 34944618, 2021). "There was induction of a variable cytokine response in respiratory tissues at different days post-infection (dpi), including TNF-α, IFN-β, IL-4, IL-6, CXCL8 (IL-8), IL-10, IL-13, CXCL10 (IP-10), CCL5 (RANTES), CXCL9 (MIG), and CCL2 (MCP-1)." (PMID 34452505, 2021). "This indirect pathway of neutralising bacteria by platelets, additionally includes the migration process of PMN and MN cells, activated by IL-8 (CXCL-8) and MCP-1 (CCL-2) secreted by activated platelets during infection with α-toxin from Staph. aureus." (PMID 34970260, 2021). "We found a marked upregulation of IFN-β, IFN-λ1, IFN-λ2/3, CXCL8, and CXCL10 in basolateral medium samples upon RSV infection compared to mock infection, starting from 24 to 48 hpi." (PMID 32878928, 2020).
infection (continued). "CXCL8 is a member of the CXCL chemokine family primarily involved in neutrophil recruitment and activation in response to tissue damage or infection and can be directly induced in human keratinocytes by dermatophytes." (PMID 33343578, 2020). "A majority (64/92) of NF-κB signaling pathway genes were downregulated more than 2-fold with infection, whereas only 5 of 92 were upregulated, BCL2A1, IL1B, CXCL8, MMP9, and SOD2." (PMID 33194960, 2020). "By contrast, we observe a reduced percentage of CXCL8-producing T cells, but comparable levels of TNF-producing T cells, from babies exposed to in utero or postnatal infection, which precedes an unstable post-natal clinical course." (PMID 32152273, 2020). "Upon infection or tissue damage, neutrophils rapidly migrate from the circulation into tissues in response to chemoattractants such as CXCL8 (IL-8)." (PMID 32854281, 2020). "In case of infection or tissue damage neutrophils migrate to the affected site in response to chemoattractants, such as CXCL8 (IL-8)." (PMID 32351713, 2020). "With the exception of CXCL8, we observed a similar RSV-mediated response in the apical wash samples, although the difference from mock infection was generally less pronounced than that observed for the basolateral medium samples." (PMID 32878928, 2020). "ERK signaling also induces inflammatory cytokine release in response to infection with RSV, with decreased levels of CXCL8 and CCL5 in supernatants of infected A549 cells treated with PD98059." (PMID 30764493, 2019). "In contrast, a significant upregulation of IL-8/CXCL8 and IP-10/CXCL10 was detected upon infection with JEV and ZIKV." (PMID 31057517, 2019). "The more upregulated pathway in the BaAka was IL-8 signaling, which mediates recruitment of pro-inflammatory cytokines (CXCL8) to sites of infection." (PMID 31200636, 2019). "Overall, lower expression of IL17, IL22, PTX3, and heterophil attracting cytokines, such as CXCL8 and VCAM1 in our data suggests a dampened innate immune response post APEC O2-GFP infection." (PMID 31998322, 2019). "On the other hand, contrary to the reports of the higher circulating level of IL-8 (CXCL8) in response to P. falciparum malaria, depressed expression of IL-8 was observed frequently during early infection." (PMID 31614626, 2019). "Infection of AECs with RSV induces the production of pro-inflammatory mediators, including pro-inflammatory cytokines IL-6 and chemotactic cytokines CXCL8 (IL-8) and CXCL10 (IP-10), which lead to the recruitment of immune cells, including neutrophils." (PMID 29712964, 2018). "The chemokine IL-8 or CXCL8 is known to be involved in the immune response to fungal pathogens and it has a primary role in recruiting neutrophils to the site of infection." (PMID 29093719, 2017). "Only GJ18 experienced any systemic pro-inflammatory response with transiently increased plasma concentrations of IL-12, CXCL8, and MIF by day 1 to 2 post-infection that rapidly resolved to baseline and later increases in CCL2 and CCL11." (PMID 29259582, 2017). "Interleukin-8 (IL-8)/CXCL8, a member of the CXC chemokine family, forms the first line in host defense by activating and recruiting neutrophils to the site of injury or infection." (PMID 28323848, 2017). "Infection activates a broad chemokine response to infection, including CXC (CXCL1, CXCL5, CXCL8, CXCL9, and CXCL10) and CC chemokines (CCL2, CCL3, and CCL5)." (PMID 26927188, 2016). "In the acute infection model, CCL2 and CXCL8 protein releases were detected in supernatants of the cells of all donors only after 9 h and were within the levels of the non-infected control HPBCs." (PMID 27446812, 2016). "Our RT-qPCR data confirmed that, upon infection with E. coli 1303, expressions of CCL20 and CXCL8 genes were induced, approx. 16 000-fold and 108-fold, respectively." (PMID 26062913, 2015). "Both CXCL8 and HMGB1 were significantly increased already after eight hours of infections with all four strains." (PMID 26601609, 2015).